HAPLN4 (hyaluronan and proteoglycan link protein 4)
Description:
Essential for the proper localization of brevican (BCAN), mainly as a perineuronal nets (PNNs)-type deposition in the brainstem and cerebellum thereby playing a key role in the formation and structural organization of PNNs (By similarity). Contributes to the formation and transmission of inhibitory GABAergic synapses between Purkinje cells and deep cerebellar nuclei neurons (By similarity).
Synonyms: BRAL2; KIAA1926
Tractability: Antibody: UniProt places it where antibodies can reach, with medium confidence; UniProt predicts a signal peptide or a membrane-spanning region; its Gene Ontology location is reachable by antibodies, with medium confidence.
Gene: Protein-coding gene on chromosome 19 (19,254,756 to 19,262,805, reverse strand). Ensembl gene ENSG00000187664.
Subcellular location: Secreted, extracellular space, extracellular matrix
Gene Ontology:
Molecular function: structural constituent of synapse-associated extracellular matrix; hyaluronic acid binding
Biological process: central nervous system development; inhibitory synapse assembly; skeletal system development; synaptic transmission, GABAergic; cell adhesion
Cellular component: gel phase of interstitial matrix; perineuronal net; synapse
Genetic constraint (gnomAD): Loss-of-function variants: 21 observed, 27.89 expected, observed/expected ratio (o/e) 0.75, 90% interval 0.53 to 1.08. The upper end of that interval is the gene's LOEUF score, 1.08, which puts it in group 4 of 6, group 1 being the genes least tolerant of losing a copy. Missense variants: 587 observed, 524.6 expected, observed/expected ratio (o/e) 1.12, 90% interval 1.04 to 1.2. Synonymous variants: 274 observed, 237.51 expected, observed/expected ratio (o/e) 1.15, 90% interval 1.04 to 1.27.
Homologues: Orthologues: chimpanzee HAPLN4 (99% identical), macaque HAPLN4 (99% identical), dog HAPLN4 (97% identical), pig HAPLN4 (95% identical), mouse Hapln4 (91% identical), rat Hapln4 (91% identical), guinea pig HAPLN4 (90% identical), tropical clawed frog hapln4 (56% identical), zebrafish hapln4 (51% identical). Paralogues in human: HAPLN1 (42% identical), HAPLN3 (42% identical), HAPLN2 (38% identical), NCAN (35% identical), BCAN (32% identical), VCAN (32% identical), ACAN (31% identical).
Diseases named in the same sentence as HAPLN4 in open-access papers:
HAPLN4 is named in the same sentence as 15 diseases in open-access papers, as found by Europe PMC text mining. Sharing a sentence is not in itself a finding about the gene and the disease. The quoted sentences say what the papers report.
glioma (2 papers, 2020 to 2024). A benign or malignant brain and spinal cord tumor that arises from glial cells (astrocytes, oligodendrocytes, ependymal cells). "Both HAPLN3 and HAPLN4 can enhance the migration of glioma cells, while HAPLN4 can strengthen the mitogenic effect of BCAN." (PMID 38791985, 2024). "HAPLN4 is obviously decreased in the parenchyma of malignant gliomas, and HAPLN4 expression promotes glioma cell adhesion and migration." (PMID 32188434, 2020).
schizophrenia (2 papers, 2020 to 2022). A major psychotic disorder characterized by abnormalities in the perception or expression of reality. "In two of these instances, overexpression was associated with both schizophrenia and BIP: HAPLN4—(schizophrenia: ZTWAS = 5.03, P = 4.66 × 10−7), (BIP: ZTWAS = 5.6506, P = 1.6 × 10−8)], and NEK4—(schizophrenia: ZTWAS = 5.34, P = 9.25 × 10−8), (BIP: ZTWAS = 5.13, P = 2.9 × 10−7)." (PMID 32398653, 2020).
astrocytomas (1 paper, 2015). "Tenascin-C, and Aquaporin-1 were significantly upregulated in astrocytoma tissues compared with NAT samples, while HAPLN4 and PPP2R2C were significantly downregulated." (PMID 26252651, 2015). "Among the mRNAs with the raw gProcessed Signal > 500, two of the 5 most upregulated mRNAs (Tenascin-C, Aquaporin-1) and two of the 5 most downregulated mRNAs (HAPLN4, PPP2R2C) were validated in the training set (40 astrocytomas and 20 NAT samples)." (PMID 26252651, 2015).
cognitive deficits (1 paper, 2024). "Thus, loss of HAPLN4 could suggest a disruption in PNN function in rTg-DI rats potentially contributing to the observed cognitive deficits." (PMID 38600214, 2024).
Hepatic steatosis (1 paper, 2026). Steatosis is a term used to denote lipid accumulation within hepatocytes. "HAPLN4 was identified as a key locus influencing hepatic steatosis in a large-scale multi-ethnic meta-analysis." (PMID 41056021, 2026).
ischemia (1 paper, 2023). A hypoperfusion of the BLOOD through an organ or tissue caused by a PATHOLOGIC CONSTRICTION or obstruction of its BLOOD VESSELS, or an absence of BLOOD CIRCULATION. "On the other hand, ischemia evoked a significant downregulation of genes associated with the protective functions of ECM molecules (e.g., brevican, Hapln4); this downregulation was also more prominent in the aged mice." (PMID 38107409, 2023).
mucopolysaccharidosis (1 paper, 2025). A group of autosomal recessive or X-linked inherited lysosomal storage disorders affecting the metabolism of mucopolysaccharides, resulting in the accumulation of mucopolysaccharides in the body. "An early genome-wide expression study on limb cartilage from 13.5-day embryonic mice and growth plate cartilage from 5-week-old mice demonstrated significant abnormalities in HAPLN4 gene expression within the growth plate tissues of mucopolysaccharidosis mouse models." (PMID 40996951, 2025).
neuroblastoma (1 paper, 2024). Neuroblastoma (NB) is the most common solid, extracranial childhood tumor. "The upregulation of genes BSG/CD147, CCDC125, GABRB3, GNB2L1/RACK1, HAPLN4, HEBP2, and HSD17B12 is associated with poor neuroblastoma prognosis and low EFS." (PMID 38398114, 2024).
psychiatric disorder (2 papers, 2025). A disorder characterized by behavioral and/or psychological abnormalities, often accompanied by physical symptoms. "While previous research has largely focused on the association between HAPLN4 and psychiatric disorders, its involvement in joint diseases remains understudied." (PMID 40996951, 2025). "HAPLN4 has been discovered to be associated with psychiatric disorders." (PMID 40868097, 2025).
HAPLN4 also shares sentences with these, for which no sentence is quoted: bipolar disorder (1 paper); brain injuries (1); coronary artery diseases (1); joint diseases (1); lung carcinoma (1); malignant glioma (1).